INS (insulin)
Diseases named in the same sentence as INS in open-access papers (continued):
Sharing a sentence is not in itself a finding about the gene and the disease.
diabetes (continued). "Diabetes, often known as diabetes mellitus, is a fatal metabolic disorder characterized by high blood sugar levels mainly due to the body either cannot use insulin effectively or does not produce enough of it." (PMID 36875845, 2023). "For example, enter the following data in the web calculator, BMI=15.30200, AST=8.225261, ALP=2.056905, GGT=2.617000, Glycosylated hemoglobin=7.242759, Insulin=0.1668287980, Ferritin=19.687883, Total cholesterol=3.12913084, Diabetes=No." (PMID 37732127, 2023). "Insulin (INS), a hypoglycemic hormone, is mainly used in the clinical treatment of diabetes." (PMID 36925675, 2023). "In people without diabetes, exendin 9-39 increased hepatic extraction of insulin slightly but significantly during fasting (0.66 ± 0.04 versus 0.70 ± 0.03, P = 0.04)." (PMID 37751301, 2023). "On the contrary, insulin-treated diabetes mellitus was the predictor of negative FFR and positive iFR/RFR discrepancy—OR (95%CI) 4.61 (1.38–15.40); p = 0.013." (PMID 36826530, 2023). "Glucose-stimulated insulin secretion, GSIS, represents one of the central processes in the regulation of the body’s glucose metabolism and homeostasis, and its deregulation leads to the development of type 2 diabetes mellitus, T2DM, and metabolic syndrome." (PMID 37107221, 2023). "Due to a lack of insulin levels or action, diabetes prevents the body from getting sufficient glucose from the blood into the body's cells to be converted into energy." (PMID 36685073, 2023). "Diabetes mellitus is a complex illness in which the body does not create enough insulin to control blood glucose levels." (PMID 36985818, 2023). "When the pancreas does not produce enough insulin or the body does not use the produced insulin effectively, blood sugar rises, leading to hyperglycemia, which can lead to diabetes." (PMID 37264332, 2023). "Whether specified diabetes types significantly explained the heterogeneity for the outcome of HOMA-IR (regression coefficient: −1·68, 95 % CI (−2·84, −0·51)) and serum insulin level (regression coefficient: −0·78, 95 % CI (−1·31, −0·25)) in the meta-analyses." (PMID 35946077, 2023). "Adolescents with PCOS and IGT had a 40% reduction in first-phase insulin secretion compared with those with PCOS and normal glucose tolerance, confirming the pivotal role of hampered β-cell function for the progression toward overt diabetes." (PMID 36980074, 2023). "Type 1 diabetes mellitus (T1DM) is a chronic autoimmune condition characterized by the irreversible destruction of the β cells of the pancreas, which leads to a lifelong dependency on exogenous insulin." (PMID 38187075, 2023). "The spectrum of causative genes (PTF1A, GLIS3, WFS1, INSR, SLC29A3, ZNF808, ABCC8, INS) is markedly different from the monogenic diabetes genes seen in non-consanguineous cohorts, and also different from those seen in other consanguineous populations." (PMID 37897565, 2023). "Currently, no real cure exists for diabetes, and daily insulin injections remain the standard of care for patients with T1DM." (PMID 36677212, 2023). "Diabetes is a disease whereby your body is not able to give you enough insulin to cover the glucose or the sugar that’s in there that came from food and other sources." (PMID 36791113, 2023). "That would be of great value since glucagon secretion and action and their role in the pathogenesis of diabetes have been understudied, compared to insulin, also due to the lack of appropriate methodologies to accurately assess them." (PMID 37030857, 2023). "For the treatment of diabetes, the current guidelines of most countries do not recommend direct injection of exogenous insulin." (PMID 37900148, 2023). "Fourteen percent had diabetes and of those, 86% were on oral medications for diabetes (none were on insulin)." (PMID 38153924, 2023).
diabetes (continued). "In the current study of a population of patients with T2DM the additive impact of NAFLD on FMD was independent of all possible confounders including age, sex, smoking status, duration of diabetes, BMI, SBP, DBP, DLP, use of statin, use of insulin, FBS, HbA1C, TG, Cholestrol, HDL, and LDL." (PMID 37749528, 2023). "Creatinine clearance was significantly decreased in MWF-C compared with Wistar (1.639 ± 0.05 vs. 3.60 ± 0.04 mL/min), with no changes in diabetes or insulin treatment." (PMID 38069331, 2023). "Diabetes mellitus is a condition in which either the pancreas no longer produces enough insulin or cells stop responding to the insulin that is produced such that glucose in the blood cannot be absorbed into the cells of the body." (PMID 37884923, 2023). "The subanalysis included participants who did not change their treatment for diabetes and did not receive insulin or insulin secretagogues during the study period." (PMID 37514025, 2023). "Studies have demonstrated high accuracy of CGM devices in individuals with diabetes, supporting the safety of CGM systems for informing treatment decisions in adults with type 1 diabetes or individuals with type 2 diabetes who are on insulin." (PMID 37687871, 2023). "Gut microbes can improve insulin sensitivity, reduce inflammation, and regulate energy metabolism, carbohydrate metabolism, lipid metabolism, and other life activities through SCFA production, thereby alleviating diabetes." (PMID 37893758, 2023). "Conventional medications, including insulin and oral antidiabetic medicines, can alleviate the signs of diabetes but cannot restore insulin release in a physiologically normal amount." (PMID 36936164, 2023). "In our study’s analysis, we found that patients who took medication three or more times a day, and those on insulin and OMAs proved to have higher PTHL level, which was expected as these patients have been exposed to a longer period of diabetes` education from the time of diagnosis." (PMID 37726735, 2023). "In people without diabetes, exendin 9-39 infusion lowered fasting insulin concentrations compared to saline infusion (47 ± 6 pmol/L versus 39 ± 5 pmol/L, P = 0.02)." (PMID 37751301, 2023). "One dog was diagnosed with overcontrol of diabetes mellitus and improved on a lower dose of insulin and had no additional documentation of urinary tract infections." (PMID 36708199, 2023). "A poor blood glucose balance among children in Tanzania probably reflects the limitations of diabetes care, including lack of insulin supply." (PMID 37033222, 2023). "If insulin or its action on tissues and cells is absent, it results in a build-up of glucose in the blood and the development of diabetes symptoms." (PMID 37999402, 2023). "In conclusions, the findings of this study indicate a quite dichotomous behavior of anticoagulated AF population with diabetes according to the use or lack of use of insulin." (PMID 35976428, 2023). "In obese people without diabetes, fasting hyperinsulinemia is found without detectable hyperglycemia, which is theoretically necessary to stimulate additional insulin secretion by beta-cells." (PMID 36902173, 2023). "Some clinical information, including the patient's type of diabetes or the type of insulin regime, were not reported in the primary studies." (PMID 37551735, 2023). "Insulin-requiring diabetes was associated with a higher risk of ischemic stroke/TIA/systemic embolism (1.81%/year) vs both no diabetes (HR 2.10, 95% CI 1.31–3.38; p = 0.002) and diabetes not on insulin (HR 2.06, 95% CI 1.18–3.62; p = 0.014)." (PMID 35976428, 2023). "They showed that hesperidin (100 mg/kg/day) improved fasting glucose and insulin sensitivity without changing fasting insulin levels, preventing IR and diabetes." (PMID 37036026, 2023). "Diabetes is a chronic disease where the body either does not produce enough insulin, a hormone that regulates blood sugar levels, or where the cells are not sensitive to the hormone." (PMID 37383944, 2023).
diabetes (continued). "Several participants made it clear, that eating habits were inevitably coined to diabetes and diabetes treatment.“If you go and snack a lot without taking insulin to cover it." (PMID 36754894, 2023). "Posthoc, we noted that the incremental increase in integrated insulin and C-peptide concentrations during the first 30 minutes of hyperglycemia was decreased by exendin 9-39 infusion in people without diabetes." (PMID 37751301, 2023). "Additionally, in type 1 diabetes mellitus (T1DM) and the advanced stage of T2DM, where impaired islet function is present, BBR increases insulin secretion and preserves pancreatic islet cells via antioxidant activity." (PMID 37371950, 2023). "The severity of diabetes may vary due to increasing doses of STZ, marked increases in serum glucose levels and progressive decreases in insulin levels over 24 h." (PMID 37990213, 2023). "We aimed to describe for the first time the localization and density of glucagon- (Glu+Cs) and insulin (Ins+Cs)-immunopositive endocrine cells in the wall of porcine DHC, DCH, DC, and VB for better understanding of the pathophysiology and treatment of diabetes." (PMID 38094502, 2023). "There was a significant decline in insulin sensitivity in the five years before the diabetes diagnosis in comparison to those who were not diagnosed with diabetes." (PMID 36984867, 2023). "Sociodemographic analysis: among the 57 study participants, 10 (17.5%) were non-diabetic volunteers and among patients with diabetes 20 (42.6%) - of which 6 (12.8%) were patients with T2D - were treated with insulin." (PMID 36818029, 2023). "Induction of diabetes by STZ could severely damage the pancreatic beta cells and subsequently decrease serum insulin levels." (PMID 36825257, 2023). "Diabetes mellitus is a type of metabolic disease in which the secretion or normal function of insulin is insufficient, and is characterized by an increase in the concentration of glucose in the blood, called hyperglycemia." (PMID 37893448, 2023). "In conclusion, we identified differential roles of CD36 in regulating muscle insulin response under conditions with and without PA overload, which provides supportive evidence for further research into therapeutic approaches to diabetes." (PMID 36979708, 2023). "Diabetes mellitus (DM) is a metabolic disease characterized by chronic hyperglycemia due to a lack of insulin secretion, insulin sensitivity/action, or both, thus requiring frequent monitoring and proper control with both lifestyle changes and pharmacotherapy." (PMID 36979709, 2023). "Insulin infusion led to a decreased LC3BII/I ratio in obese and lean individuals, but not in diabetic patients, indicating that insulin is capable of inhibiting autophagy in conditions other than diabetes." (PMID 37876013, 2023). "Short-term (2 weeks to 3 months) insulin intensive therapy using continuous subcutaneous insulin infusion (CSII) can improve islet beta cell function and prolong glycemic remission in patients with newly diagnosed type 2 diabetes mellitus (T2DM)." (PMID 37489121, 2023). "A reduced 30 mg edoxaban daily dose was given in 22% of patients without diabetes, 26% of diabetic patients not on insulin and 38% of those on insulin; the prevalence of a concomitant antiplatelet treatment at baseline was 14.7, 17.2 and 17.2%, respectively." (PMID 35976428, 2023). "Type 2 diabetes mellitus (T2DM) accounts for nearly 90% of diabetes mellitus (DM) worldwide and is a chronic metabolic disorder characterized by hyperglycemia which is triggered by dysfunction of insulin secretion or insulin resistance." (PMID 37032867, 2023).
diabetes (continued). "In a retrospective cohort study, thirty-day mortality was lowest in SARS-CoV-2 residents taking metformin (12.6%, n = 12) compared with those on other diabetes medications (17.4%, n = 12), insulin (23.3%, n = 24), and no diabetes medications (22.7%, n = 108)." (PMID 37893528, 2023). "Recently, Azam and co-authors have carefully reviewed the possibility of designing and using IDE inhibitors as a valid alternative to treat diabetes rather than using injected exogenous insulin." (PMID 37892174, 2023). "Disruption of hepatic insulin signalling induces NAFLD and hepatic insulin resistance through insulin receptor substrate-2 gene deletion, leading to upregulation of SREBP-1, leading to the development of obesity, diabetes and NAFLD in laboratory animals." (PMID 37360298, 2023). "Diabetes mellitus is the condition of hyperglycemia and derangement in carbohydrates, proteins, and fats due to the lack of insulin." (PMID 37143509, 2023). "Among the published cases, the youngest was a premature infant with SDS who developed autoantibody-negative diabetes mellitus at the age of three months due to slowly progressive hyperglycemia requiring insulin treatment 12 months later." (PMID 37580732, 2023). "As mentioned in the 2019 AGS Beers Criteria, it is not recommended to use a sliding scale insulin formulation (rapid acting or short acting) as the only treatment for diabetes, rather than other basic insulin or long-acting insulin." (PMID 38001406, 2023). "Subcutaneous insulin injection is the mainstay treatment for diabetes mellitus which often leads to non-compliance among patients, especially in younger patients." (PMID 36979643, 2023). "The “Diabetes Mellitus on insulin” component of the score does not accurately reflect the severity of the disease." (PMID 37035307, 2023). "In people without diabetes, these defects are no longer apparent in response to hyperglycemia, although the initial insulin secretory response to hyperglycemia is impaired." (PMID 37751301, 2023). "In fact, diabetes requiring insulin therapy, rather than the presence of diabetes per se, appeared to be an independent factor affecting the occurrence of thromboembolic complications during follow-up." (PMID 35976428, 2023). "Although insulin does not affect the activity of class 3 PI3Ks, it also has promise as a target for diabetes treatment because of its role in the feedback loop of glucose homeostasis." (PMID 38983593, 2023). "Clustering of 1269 subjects without diabetes was performed with oGTT-derived glucose and insulin; fasting triglyceride, high-density lipoprotein, BMI, waist and hip circumference." (PMID 37592260, 2023). "We also did not have the power to distinguish between individuals using insulin into subgroups according to their diabetes type, and how well controlled their dysglycemia was." (PMID 37798236, 2023). "It is possible that education regarding diabetes, which is still lackluster in Peru, does not guide patients in the early use of insulin." (PMID 37377235, 2023). "Second, since we didn’t check the serum insulin and c-peptide levels, there is no information on hyperinsulinemia, the pathogenesis of diabetes, and MetS." (PMID 36696408, 2023). "Additional research has found that individuals with continuous subcutaneous insulin infusion (CSII) and CGM experience significant reductions in the occurrence of diabetes-related hospitalizations compared to individuals with CSII and the use of traditional blood glucose monitoring." (PMID 40303275, 2023). "Older traditional treatments concentrated solely on insulin level regulation without addressing diabetes complications, but newer therapeutic approaches not only alleviate symptoms, but also improve organ function." (PMID 37375806, 2023). "In this perspective, the ideal IDE inhibitor to treat diabetes should inhibit the clearance of insulin and amylin without affecting the catabolism of other IDE substrates, such as glucagon or amyloid beta peptides." (PMID 37892174, 2023).
diabetes (continued). "The results of this study proposed that the microbial medium of CLM might reduce blood sugar, especially FBG and insulin tolerance, and its effect could be helpful for patients with impaired FBG or pre-diabetes." (PMID 36934269, 2023). "Diabetes Control and Complications Trial (DCCT) has shown that family history of T2DM in patients with T1DM had greater development of obesity, require higher insulin dose, and abnormal lipid profile." (PMID 38111445, 2023). "Type 1 diabetes mellitus (T1DM) is a chronic metabolic disease characterized by the insufficient or absent production of insulin, due to β-cell destruction, which can result in hyperglycaemia." (PMID 37367780, 2023). "Unlike the β-cells that are affected in type 1 diabetes mellitus through autoimmunity, impairment of insulin secretion in T2DM occurs in a multifactorial, non-autoimmune process." (PMID 37745252, 2023). "Between 2017 and 2019, less than 10% of pregnancies treated for pregestational diabetes continued metformin rather than switching to insulin." (PMID 37206113, 2023). "Although the majority of patients had no family history of diabetes (69.1%), nearly half of the patients required either mono-insulin or combination therapy (48.6%)." (PMID 37858125, 2023). "From our existing database of 350 patients with diabetes managed according to our liberal glucose control protocol we excluded 245 patients (218 not receiving insulin, 16 with less than 10 blood gases, and 11 with type 1 diabetes)." (PMID 36263915, 2023). "The clinical characteristics of the four affected family members were indicative with a diagnosis of MODY; they were non-obese, and their diabetes was non-insulin-dependent." (PMID 37711893, 2023). "Although impaired insulin secretion and sensitivity are associated with an increased risk of diabetes, enhanced insulin levels and secretion rates in BPA-exposed pancreatic β-cells do not indicate increased insulin sensitivity." (PMID 38132710, 2023). "Another patient concern pertains to not giving their diabetes enough attention by properly taking their insulin so that they now face significant health issues that affect their daily life." (PMID 38041170, 2023). "No overt diabetes was observed but a third (16/49) of our HG-positive LT cohort was treated with insulin." (PMID 36824650, 2023). "In particular, both exercise mode and sex affect glucose sensitivity and insulin clearance in those without diabetes." (PMID 36833469, 2023). "The GIPR SNP rs10423928 was associated with the 2-h glucose level and the AUC ratio of insulin and glucose after an OGTT in participants without diabetes." (PMID 37049537, 2023). "Therefore, CGM is recommended for patients with preexisting diabetes in pregnancy (especially T1DM complicated with pregnancy), GDM requiring insulin treatment, large blood glucose fluctuation, and potential nighttime hypoglycemia." (PMID 37680884, 2023). "Diabetic ketoacidosis is a grievous complication of diabetes that occurs when there is a lack of insulin in the body, resulting in elevated blood glucose levels and the production of ketones." (PMID 37363479, 2023). "Diabetes is when the sugar is very high when tested and it indicates a high glucose level in the blood which means that the insulin is not enough to break down the sugar that comes into your blood...”." (PMID 37976282, 2023). "Extraordinary weight reduction together with fat reduction in the liver and pancreas did not lead to diabetes remission in the Diabetes Remission Clinical Trial (DiRECT) study unless glucose-stimulated acute insulin secretion had been restored." (PMID 39872624, 2023). "In the sensitivity analysis subclassifying diabetes as insulin dependent and not insulin dependent, 784 and 1688 events were observed, respectively." (PMID 37071420, 2023). "Literature on the combined usage of GLP1-RAs and insulin in DKD is limited, but their concurrent use in diabetes is promising and could significantly reduce UACR." (PMID 37090383, 2023).